POSTN (periostin)
Diseases named in the same sentence as POSTN in open-access papers (continued):
Sharing a sentence is not in itself a finding about the gene and the disease.
tumor (continued). "Interestingly, the tumours with Periostin expression significantly showed higher number of vessels (high blood vessel density) than those without Periostin expression (P<0.005)." (PMID 17060937, 2006). "Furthermore, patients co-expressing high levels of POSTN and p-ERK1/2 exhibited a more aggressive tumor phenotype: Compared with patients with low expression of these two molecules, they showed greater depth of tumor invasion, higher rates of lymph node metastasis, and more distant metastases." (PMID 41018265, 2025). "In addition to its intrinsic effects on GSCs, POSTN can recruit microglia and upregulate CD70 expression in microglia through the αVβ3/PI3K/AKT/NFκB pathway, which in turn promotes Treg development and functionality and supports the formation of an immunosuppressive tumor microenvironment." (PMID 39227950, 2024). "However, the tumor stromal load did not correlate with POSTN staining intensity." (PMID 36765091, 2023). "Therefore, we hypothesized that miR-876 and POSTN may enhance the invasion of tumor cells in situ via EMT and disrupt ECM homeostasis via fibrogenesis to form a favorable metastatic microenvironment, thus inducing tumor progression and poor prognosis." (PMID 33083453, 2020). "Furthermore, CAFs are capable of stimulating tumor invasion by inducing structural changes in the ECM, including stimulation of neuropilin-1, a co-receptor and signaling amplifier of a variety of VEGF family proteins, MMP-1, MMP-2 and MMP-9, promoting matrix degradation, periostin and tenascin C." (PMID 31450710, 2019). "Therefore, people may question whether the increased POSTN is induced by activation of TGF-β signaling pathway rather than a concomitant phenomenon, as TGF-β3 could promote EMT in cancer cells directly to facilitate tumor metastasis." (PMID 26857387, 2016). "However, the high expression level of POSTN was not correlated with gender, age or tumor location." (PMID 26023718, 2015). "However, the over expression of POSTN protein was not related to gender, age or tumor location." (PMID 26023718, 2015). "However, there is no study on the role of periostin in tumor lymphangiogenesis." (PMID 22952986, 2012). "In fact, 14 of 23 (61%) cases showed patterns I and II (a solid sheet of tumour with a pushing border and large tumour islands) and no cases showed pattern IV in Periostin-negative cases, suggesting that Periostin-negative cells may not be able to detach from tumour nests." (PMID 17060937, 2006). "Both POSTN and PDPN were absent in normal testes, but immunohistochemically present in most tumours, clearly indicating their role in testicular carcinogenesis." (PMID 41361308, 2025). "Consistently, we observed a positive correlation between POSTN expression and ESTIMATE score, and a negative correlation with tumor purity." (PMID 38389400, 2024). "Knockdown of POSTN, but not FN1, significantly slows the migration rate of ALK/MYCN tumor cells in filling the wounded area." (PMID 38451815, 2024). "Fibrillar proteins (collagen, fibronectin, laminins, and periostin) are not abundant in normal brain matrix but increase in the glioma ECM, predominantly around vessels providing tumor cells adhesion and migration." (PMID 39768176, 2024). "By comparing the bulk tumor with the peritumoral area, we found a significant up-regulation of all the three ECM proteins, POSTN, TnC, and OPN, in the TRS in both the MetS and non-MetS iCCA." (PMID 36902188, 2023). "In a mouse model, TNBC tumor-bearing mice exhibit an enhanced expression of extracellular matrix proteins, such as fibronectin, tenascin-C, and periostin, in the lungs compared to non-TNBC tumor-bearing mice." (PMID 36835116, 2023). "Although the role of YY1 in cancer is controversial, with both oncogenic and tumor suppressor roles, YY1 acts as a strong negative regulator of periostin expression." (PMID 35954468, 2022).
tumor (continued). "The non-cellular components of TME such as tenascin, periostin, SPARC, and collagen which overall contribute to the fitness of the tumor tissue, are mainly released by CAFs." (PMID 39086964, 2022). "Contrary to periostin, MGP has not attracted much attention in the field of oral pathology and neoplasia." (PMID 34205668, 2021). "We defined the grading of periostin and VEGF-C staining as high (over 10% of tumor cells showing ++ or +++ intensity) or low (no staining or less than 10% of tumor cells showing + intensity)." (PMID 22952986, 2012). "Interestingly, cells expressing POSTN transcripts (ON) in MEEI16 tumor expressed multiple common and variable p‐EMT genes at higher levels compared to cells not expressing POSTN (OFF)." (PMID 36691359, 2023). "Interestingly, 5 existing markers (ACTA2, VIM, S100A4, POSTN, PDPN) are not specific for any of the 9 tumor types we studied." (PMID 36263012, 2022). "In addition, there were no noticeable changes in tumor suppression, proliferation, or epithelial-to-mesenchymal transition (EMT), as reflected by Loxl4, periostin, and E-cadherin expression levels." (PMID 31727800, 2019). "Gene silencing of periostin (POSTN), responsible for cell survival, invasion and angiogenesis, reached higher values in siRNA/RGD-chitosan NP treated tumors than NP without RGD and additionally the tumor growth was more inhibited." (PMID 24276320, 2013). "Periostin also interacts with various cell-surface receptors, most notably integrins, and signals mainly via the PI3-K/Akt and other pathways to promote cell growth, cell survival, epithelial—mesenchymal transition (EMT), invasion, tumor angiogenesis and metastasis." (PMID 25781169, 2015).
cancer (424 papers, 2006 to 2026). A tumor composed of atypical neoplastic, often pleomorphic cells that invade other tissues. "As the disease advanced, Fib_FBLN1+ fibroblasts—associated with tissue repair and homeostasis gradually transitioned into cancer-associated fibroblasts (CAFs), including Fib_POSTN+, Fib_CD74+, and Fib_CXCR4+ subpopulations." (PMID 40948762, 2025). "By analyzing multiple scRNA‐seq and spatial transcriptomic datasets, we identified a unique subset of CXCL14+ myofibroblastic CAFs (myCAFs), emerging during the early differentiation phase of pan‐cancer invasiveness‐associated THBS2+ POSTN+ COL11A1+ myCAFs." (PMID 40162549, 2025). "Periostin has been shown to be abnormally expressed in cancer-associated fibroblasts (CAFs) across various cancer types and is regulated by the TGFβ/Smad signaling pathway." (PMID 39941916, 2025). "High expression of POSTN in CAFs was associated with poor prognosis in various cancers, including breast, cervical, CRC, oesophageal cancers (EAC), and PDAC." (PMID 39780187, 2025). "As an extracellular matrix protein, periostin is implicated in key roles in pathways related to autoimmune diseases, particularly those affecting the skin and lungs, as well as in cancers." (PMID 39728072, 2024). "Cancer-associated fibroblast (CAF)-derived POSTN promotes papillary thyroid tumor growth in vivo and in vitro." (PMID 38773979, 2024). "POSTN-encoded protein can promote cancer stem cells stemness maintance and support the adhere and migration of epithelial cells." (PMID 39239507, 2024). "POSTN has been previously implicated in resistance formation in different cancers in response to a variety of therapeutic approaches." (PMID 38942020, 2024). "These fibrosis‐associated ECM, such as type IV collagen, periostin, promote cancer cell proliferation, migration, and apoptosis resistance, confer resistance to starvation and hypoxia, and limit the delivery of chemotherapeutic drugs to cancer cells." (PMID 37937304, 2023). "Among these DEGs, SPOCK1 and POSTN were identified as key prognostic genes and mainly expressed in cancer-associated fibroblasts for CRC." (PMID 36611136, 2023). "In a preclinical murine model, cancer-associated fibroblast (CAF)-derived POSTN regulated the function of LECs and promoted the implantation of metastatic cells in the lymph nodes." (PMID 37234990, 2023). "CTHRC1 specifically activated PSC into myofibroblast-like cancer-associated fibroblasts (myCAFs), which are characterized by a significantly upregulated POSTN gene expression." (PMID 37444482, 2023). "Elevated expression of POSTN and of the periostin protein have been reported in cancer cells and in the TME16 and are associated with poor prognosis as well as resistance to chemotherapeutic treatments, including in OC18." (PMID 38049490, 2023). "POSTN is also produced by cancer-associated fibroblasts (CAFs), and its expression seems to be upregulated in several pathologies, such as inflammation, tissue repair, and malignant transformation." (PMID 38076555, 2023). "We have shown that higher expression of periostin in cancer cell conditioned medium is associated with an increase in phospho-AKT levels, and that this is reduced by the addition of the AKT inhibitor MK-2206." (PMID 38049490, 2023). "Periostin (encoded by POSTN) is a matricellular protein overexpressed in cancers including NSCLC compared to normal tissues." (PMID 38115703, 2023). "Extracellular matrix cancer-associated fibroblasts sum up another recently discovered major fibroblast subpopulation characterized by the expression of Periostin." (PMID 37686288, 2023). "Although the multifaceted roles of periostin on cancer cells were elucidated, the association of POSTN+ CAFs with other stroma cells including macrophages, and the influence on T cell infiltration remains to be explored." (PMID 38115703, 2023).
cancer (continued). "In vitro and in vivo studies reported that periostin expression is associated with the aggressive characteristics of cancer cells including proliferation, invasion and metastasis, angiogenesis, drug resistance and avoiding immune destruction." (PMID 36830807, 2023). "POSTN (periostin), known to be secreted from cancer-associated fibroblast (CAF), and wingless-type MMTV integration site family member 10B (WNT10B), which promote EMT, were also found to be inhibited by the PT complex." (PMID 38027033, 2023). "In BCa, immunohistochemistry results indicated that POSTN was overexpressed mainly in cancer-associated stroma and/or slightly in cancer cells, usually associated with poor clinical outcomes." (PMID 35831854, 2022). "While POSTN (Periostin) associates with epithelial–mesenchymal transitions in cancer and the differentiation of mesenchyme, FAP controls fibroblast growth or epithelial–mesenchymal interactions during development, tissue repair, and epithelial carcinogenesis." (PMID 35742914, 2022). "High stromal periostin expression was significantly associated with significantly shorter overall and cancer-specific survival based on the log-rank test (p < 0.0001, each)." (PMID 35850759, 2022). "Emphasis is placed on its association with cancer progression, and also future potential for periostin-targeted therapeutic approaches will be explored." (PMID 36224629, 2022). "POSTN-encoded protein binds to integrins to support adhesion, migration of epithelial cells, and participation in cancer stem cell maintenance and metastasis." (PMID 36120433, 2022). "In cancer periostin has been associated with the regulation of cell survival, invasion, angiogenesis, metastasis, and the epithelial-mesenchymal transition." (PMID 36531007, 2022). "Periostin is a matricellular protein secreted by cancer‐associated fibroblasts and the interaction between periostin and PTK7 regulates the canonical Wnt signaling pathway." (PMID 35257502, 2022). "Chemotaxis, flow cytometry and cytokine array analyses were undertaken to analyze the involvement of POSTN in cancer-associated fibroblast (CAF) and macrophage modulation." (PMID 36550569, 2022). "Different markers, such as a-SMA, FAP, PDGFR-β, periostin, have been used for the detection of cancer-associated fibroblasts (CAFs)." (PMID 36139552, 2022). "POSTN is a secreted extracellular matrix protein, which is usually associated with poor prognosis in cancers." (PMID 36172351, 2022). "Periostin is an extracellular matrix protein that has been known to be implicated in fibrillogenesis and cell migration, including cancer metastasis." (PMID 35850759, 2022). "TGF-β3 signalling promotes periostin expression by cancer-associated fibroblasts (CAFs), resulting in growth, migration and invasion of cancer cells." (PMID 34205668, 2021). "In gene expression profiling, POSTN is expressed at the mRNA level in cancer-associated fibroblasts." (PMID 33919736, 2021). "Previous research also revealed that POSTN was associated with carcinoma invasion and metastasis 16, which provide a potential target for cancer metastasis treatment." (PMID 34093819, 2021). "Many researchers have demonstrated that cancer-associated fibroblasts (CAFs) secrete periostin, which promotes cancer initiation and progression." (PMID 34702952, 2021). "Periostin (PN) is a stromal protein which is mostly secreted from cancer associated fibroblasts in the tumor microenvironment and can promote cancer progression including cell survival, metastasis, and chemoresistance." (PMID 33446140, 2021). "Further, high expression of periostin is observed in many carcinomas, including NSCLC, and is a factor associated with poor prognosis." (PMID 34702952, 2021). "Activation of the Erk pathways and the cross-talk with EGF signals have both been proposed as the underlying mechanism of how periostin accelerates proliferation of cancer cells." (PMID 32000779, 2020).
cancer (continued). "POSTN encodes for periostin, which was highly expressed in these cancers as demonstrated by immunohistohemistry (IHC)." (PMID 33114328, 2020). "This relationship between periostin and tenascin-c is linked to their association with lung metastasis and promotion of cancer cell migration, proliferation and invasion." (PMID 31936750, 2020). "Periostin is also implicated in the metastases of cancer cells and lymph- and angiogenesis (reviewed in:." (PMID 31936272, 2020). "Strategies to target the peptide portion of periostin as a diagnostic or therapeutic biomarker for cancer are limited due to increased expression of periostin in non-cancerous inflammatory conditions." (PMID 30911061, 2019). "Periostin, a 90kDa secreted extracellular matrix protein, is critical for determination of cell fate, proliferation and migration of cancer cells, and has been implicated in inflammatory disease including cardiovascular disease." (PMID 31374110, 2019). "POSTN has been reported to play a role in many cancers and has been seen in cancer associated fibroblasts of IDC and high-grade tumors which again is in accordance with our data." (PMID 30647841, 2018). "Several studies indicated that periostin overexpression appears to occur mainly in cancer-associated stroma." (PMID 29161296, 2017). "Overexpression of periostin has been implicated in many types of cancer such as gastric, colon, esophageal, ovarian, thyroid, lung, breast and head and neck carcinomas." (PMID 28754000, 2017). "Periostin is an extracellular matrix protein that is implicated in the biology of normal bone remodeling and in different cancer cell growth and metastasis." (PMID 27716740, 2016). "The matrix-specific protein periostin (POSTN) is up-regulated in human cancers and associated with cancer growth, metastasis and angiogenesis." (PMID 26857387, 2016). "Initially, periostin was associated to cancer as high expression levels were found in patient samples of common solid tumor types such as breast, colon, lung, and pancreatic cancer, as well as melanoma." (PMID 26539408, 2015). "Expression of versican and periostin were frequently accentuated toward the pseudo-basement membrane of the extracellular matrix around these carcinomas, and high stromal vimentin is associated with higher grade." (PMID 25852822, 2015). "Of specific interest is the induction of TPM1, TPM2, TNC and POSTN, suggesting a fundamental reprogramming of lung fibroblasts such that the cells exhibit a gene expression profile that is typical for carcinoma-associated fibroblasts." (PMID 25924783, 2015). "A recently described molecule involved in metastasis is periostin, an extracellular matrix protein secreted in response to mechanical stress and tissue repair by pericryptal and cancer associated fibroblasts (CAFs)." (PMID 24901008, 2014). "Studies have associated periostin with epithelial-mesenchymal transition (EMT) in cancer and with mesenchymal differentiation in the developing heart." (PMID 20109226, 2010). "In conclusion, periostin from cancer-associated fibroblasts might be associated with the malignant progression of CRC via Smad2/3 signaling." (PMID 39941916, 2025). "Using scRNA-seq data, we investigated the expression of genes involved in stromal-like signature (FAP, VIM, and ITGB1); cancer-associated fibroblasts (CAFs; POSTN and ACTA2); as well as COL1A1, SULF1, TCF21, and DLK1, which were previously associated with FAP-high or FAP-low CAF phenotypes in OC." (PMID 39634630, 2024). "Additionally, high levels of periostin in serum are associated with the poor prognosis of a variety of cancers." (PMID 36598904, 2023). "This is the first report of cancer cell‐specific splicing variant of POSTN." (PMID 36691359, 2023). "In addition, the CK6-positive tumors showed significantly less plasma cell infiltration and more cancer-associated fibroblasts (CAFs) expressing Periostin and SMA." (PMID 36971797, 2023).